ENSG00000275625
Gene: Miscellaneous RNA gene on chromosome X (74,281,703 to 74,281,849, forward strand). Ensembl gene ENSG00000275625.
Gene Ontology:
Biological process: positive regulation of gene expression